MYD88 (MYD88 innate immune signal transduction adaptor)
Diseases named in the same sentence as MYD88 in open-access papers (continued):
Sharing a sentence is not in itself a finding about the gene and the disease.
B cell deficiency (3 papers, 2022 to 2023). A broad classification of disorders where circulating numbers of B lymphocytes are decreased or ineffective. "B cell deficiency, or the loss of B-cell-specific CD19 or MyD88 expression, resulted in an early shift from immune regulation towards inflammation at the fetomaternal interface and fetuses, resulting in PTB." (PMID 38003279, 2023). "Moreover, B cell deficiency can significantly ameliorate NASH phenotypes in mice, possibly because both B cell receptor-mediated adaptive immune signaling and myeloid differentiation primary response 88 (MyD88)-dependent innate immune response are involved in pathological actions of B cells on NASH." (PMID 36032141, 2022).
brain injury (3 papers, 2014 to 2022). Acute and chronic (see also brain INJURIES, CHRONIC) injuries to the brain, including the cerebral hemispheres, CEREBELLUM, and brain STEM. "TLR4/MyD88 signalling is important for the development of post-operative- and post-traumatic brain injury-induced cognitive dysfunction in rats and mice, and glial modulators are currently being trialled for the potential to attenuate post-operative cognitive dysfunction." (PMID 26332828, 2015). "Knockdown of MyD88 attenuated the mRNA expression of TNF-α and inducible nitric oxide synthase (iNOS) in AD, while reduced inflammatory response was observed in MYD88 knockdown mice with traumatic brain injury (TBI)." (PMID 35873459, 2022).
brain tumors (3 papers, 2007 to 2025). "Rapid genotyping of MYD88 L265P and CD79B Y196 mutations is quite effective for intraoperative molecular diagnosis of PCNSL because it is sometimes difficult to distinguish PCNSL from inflammatory changes or other brain tumors." (PMID 36478416, 2023).
C. perfringens infection (3 papers, 2023 to 2025). "A previous study reported that the ileal TRAF6, NF-κB, and MyD88 expressions were up-regulated in piglets exposed to Clostridium perfringens infection, suggesting that the MyD88/NF-κB signaling pathway is closely related to host immune response induced by infection." (PMID 36865532, 2023). "In addition, a study on the host immune response induced by C. perfringens infection in pig ileum indicated that, unlike the jejunum, C. perfringens was able to activate the TLR4/MyD88/NF-κB signalling pathway in the ileum, activating downstream immune-related cytokines." (PMID 40869997, 2025).
cancer of the skin (3 papers, 2016 to 2022). "A large number of studies have shown that the adaptor protein MyD88 contributes to carcinogenesis, including cancer of the skin, liver, pancreas, and colon, by acting downstream of Toll-like receptors (TLRs) or the IL1 family." (PMID 35189958, 2022). "Myd88 involvement by acting downstream of TLRs in carcinogenesis was shown in many reports concerning cancer of the skin, pancreas, liver, colon, sarcoma, whereas the data about the mRNA role of MYD88 expression in tumors are limited." (PMID 33669782, 2021). "Targeted ablation of MyD88 in basal keratinocytes reduced skin tumor load by half, further confirming a direct tumor-promoting role of IL-1R/MyD88 signaling within skin cells." (PMID 31051015, 2016). "Activation of K-Ras, a potent oncogene that drives the development of multiple cancers, in transformed skin cells resulted in production of IL-1α, which signals in an autocrine manner through IL-1R/MyD88/NF-κB pathway to synergize with K-Ras for the oncogenic progression of skin cancer." (PMID 31051015, 2016).
cerebral malaria (3 papers, 2014 to 2016). A sequestration of Plasmodium falciparum in the brain, which can cause coma and/or seizures. "In the studies that have reported a protective effect of TLR9 disruption, cerebral malaria was still more severe than that observed in MYD88-deficient mice, suggestive of signalling contributions from other MYD88-dependent pathways." (PMID 25192715, 2014). "In contrast to these results, another group showed the contrary: cerebral malaria pathogenesis seems to be mediated by MyD88 signaling and its absence increases survival." (PMID 27110574, 2016). "berghei’ hereafter) infection of the C57BL/6 mouse, in which Type I inflammation promotes a lethal infection with neurological symptoms consistent with cerebral malaria, a deficiency in either TLR9 or MYD88 partially protects against lethal disease." (PMID 25192715, 2014). "However, in contrast to findings with TLR9- and MYD88-deficient mice, in the only study to examine the role of TLR7-deficiency in cerebral malaria, TLR7 was found to be irrelevant for precipitation of fatal disease." (PMID 25192715, 2014). "Importantly, unlike the synergistic interaction between TLR7 and TLR9 suggested by the survival data, these results are consistent with a model in which TLR7 and TLR9 signal redundantly through MYD88 to promote cytokine production during experimental cerebral malaria." (PMID 25192715, 2014). "Results showed that mice deficient in TLR1, TLR2, TLR3, TLR4, TLR6, TLR7, or TLR9 and their adapter proteins MyD88, TIRAP, and TRIF were as susceptive to cerebral malaria as their wild-type counterparts." (PMID 27110574, 2016).
colorectal adenocarcinoma (3 papers, 2017 to 2021). The most common type of colorectal carcinoma. "Because an increased expression of TLR4 in CRC is common and TLR4/MyD88 signaling is associated with poor prognosis, we analyzed TLR4 expression in colorectal adenocarcinoma specimen according to MMR status." (PMID 34026821, 2021). "The increased expression of TLR4 is a common feature of colorectal adenocarcinoma and TLR4/MyD88 signaling has been associated with poor prognosis." (PMID 34026821, 2021). "Nevertheless, MYD88 c.T778C was found neither in the plasma of GBM patients nor in colorectal adenocarcinoma (CRC) patients." (PMID 28636991, 2017).
corneal infection (3 papers, 2011 to 2019). A viral or bacterial infectious process affecting the cornea. "In the current study, we examined the intrinsic role of TLR signaling in ocular surface tissues by determining baseline levels of inflammatory mediators, the response to mechanical stimuli, and corneal infection in MyD88 and IL-1R-deficient mice." (PMID 28796783, 2017). "Here, we examined the intrinsic role of TLR signaling in ocular surface tissues by determining baseline levels of inflammatory mediators, the response to mechanical stimuli, and corneal infection in MyD88-deficient mice (MyD88-/-)." (PMID 28796783, 2017). "However, that appears unlikely as corneal infection with vesicular stomatitis virus does not drive detectable pVEGFA-GFP reporter expression in reporter mice despite activation of MyD88- and TRIF-dependent TLRs as well as other pattern recognition receptors such as LRRFIP1 and RIG-I." (PMID 21998580, 2011).
diabetic cardiomyopathy (3 papers, 2022 to 2025). Diabetic cardiomyopathy is a disorder of the heart muscle in people with diabetes. "Compared with diabetic cardiomyopathy mice unfed with gut content, the expression of occludin, the cardiac function, and the number of goblet cells in diabetic cardiomyopathy mice fed by gut contents were higher, whereas TLR4/MyD88 pathway-related proteins and cardiomyocyte hypertrophy were reduced." (PMID 40362425, 2025).
fibrosarcoma (3 papers, 2018 to 2022). A malignant mesenchymal fibroblastic neoplasm affecting the soft tissue and bone. "Under LPS treatment, TAMs isolated out of murine fibrosarcoma showed impaired MyD88-dependent NF-κB activation and activation of the MyD88-independent IRF-3 pathway." (PMID 32486098, 2020). "Another model worth discussing is the MCA-induced fibrosarcoma where MyD88-dependent inflammation was shown to promote tumorigenesis." (PMID 30150983, 2018). "For example, MyD88 was shown to promote tumor growth in the MCA-induced fibrosarcoma model, while simultaneously mediating a protective host response via TNFα and IFN-α/β signaling." (PMID 30150983, 2018). "In fibrosarcoma cells, IRF3 and IRF7 mRNAs were detected, while IRF1 and MyD88 mRNAs were regulated." (PMID 35737804, 2022).
gastric ulcer (3 papers, 2021 to 2025). An ulcerated lesion in the mucosal surface of the stomach. "By contrast, pre-treatment of gastric ulcers mice with DPHs decreased the expression of proteins associated with the TLR4/MYD88/NF-κB signaling pathway, decreased the activities of inflammation-related enzymes, iNOS, and COX-2, and the production and release of inflammatory factors." (PMID 34249268, 2021). "Numerous studies demonstrate that the TLR-2/MyD88 signaling pathway is critical for the formation and progression of gastric ulcers." (PMID 40563542, 2025). "Thus, it is plausible that the pathogenesis of stress-induced gastric ulcer involves the TLR4/MyD88/NF-κB signal transduction pathway." (PMID 33628315, 2021).
gram-negative bacterial infections (3 papers, 2011 to 2020). Infections caused by bacteria that show up as pink (negative) when treated by the gram-staining method. "We show Gram-negative bacterial infection upregulates Siglec-E expression via the TLR4/MyD88/JNK/NF-κB/AP-1 signaling pathway, whereas infection with Gram-positive bacteria downregulates Siglec-E expression via the TLR2/RANKL/TRAF6/Syk signaling pathway." (PMID 32889432, 2020). "This is consistent with MyD88 being particularly important for initiating host response to Gram-negative bacterial infections." (PMID 26510639, 2015).
gram-positive bacterial infections (3 papers, 2012 to 2016). Infections caused by bacteria that retain the crystal violet stain (positive) when treated by the gram-staining method. "Interestingly, transcription of TLR2 and MyD88 are both coordinately up-regulated during human neonatal Gram-positive infection in vivo, highlighting how our murine model recapitulates the human neonatal response to Gram-positive bacterial infection." (PMID 22970147, 2012). "Similar to mammalian MyD88, Drosophila MyD88 can activate the classical Toll pathway and induce AMP expression in response to fungal and Gram-positive bacterial infections." (PMID 23405063, 2013). "Both Dif RNAi and Myd88 RNAi lines showed no significant expression of drosomycin in non-infected and as well as Gram-positive bacterial infection conditions." (PMID 27819340, 2016).
helminth infection (3 papers, 2011 to 2014). "We demonstrate that granuloma formation is inhibited by a pathway involving IL-1R1, type 1 IFNR signaling, and MyD88, but distinct MyD88-dependent mechanisms maintain susceptibility to helminth infection in wild-type mice." (PMID 25114104, 2014). "MYD88 is also implicated in the immune response to Bacteroides fragilis, Plasmodium berghei and helminth infections." (PMID 22072984, 2011). "The fact that H. polygyrus also suppresses Citrobacter-induced KC expression in MyD88 KO mice suggests that the helminth infection is acting on a MyD88-independent mechanism of KC expression." (PMID 25010669, 2014). "Our data further showed up-regulation of IL-10 in co-infected WT mice, indicating that helminth infection acts on a MyD88-dependent mechanism of colonic IL-10 response." (PMID 25010669, 2014). "Histological examination of colonic tissue of co-infected mice shows that a concurrent intestinal helminth infection exacerbates bacteria-induced mucosal injury in both B6 and MyD88 knockout mice." (PMID 25010669, 2014). "With all this information taken together, this report demonstrates the importance of both TLR-dependent and -independent signals through MyD88 in the control of host resistance following helminth infection." (PMID 25114104, 2014). "In addition to inhibition of antimicrobial peptide expression, both MyD88 deficiency and helminth infection have been shown to impact on autophagy-mediated killing of bacterial pathogens, which may be another mechanism contributing to impaired defense against invading bacterial enteropathogens." (PMID 25010669, 2014). "Our data demonstrate a critical role for the MyD88 signaling pathway in host survival during helminth and enteric bacterial co-infection, and also suggest that helminth infection impairs MyD88-independent responses activated by TLR4." (PMID 25010669, 2014). "We determined the role of MyD88 signaling in controlling intestinal mucosal immune and inflammatory responses against intestinal bacterial pathogen during concurrent helminth infection." (PMID 25010669, 2014). "In this current study, we have examined the influence of intestinal helminth infection on host innate immunity and the pathogenesis of C. rodentium infection using MyD88 knockout mice." (PMID 25010669, 2014). "To gain further mechanistic insight into how helminth infection impairs host defenses against concurrent infection with an enteric bacterial pathogen, we have used MyD88 knockout mice in this study." (PMID 25010669, 2014). "Further real time quantitative RT-PCR analysis of colonic tissues showed the helminth-infection induced down-regulation of TNF-α expression in both wild-type and MyD88 knockout mice with H. polygyrus-infection, suggesting the impact of helminth infection on TNF-α expression is MyD88-independent." (PMID 25010669, 2014). "Together, these findings lead to the intriguing hypothesis that a component of the microbiota, signaling via IL-1R and MyD88, may function to inhibit granuloma formation in response to helminth infection." (PMID 25114104, 2014). "The data from this current study provides evidence to indicate the possibility that in MyD88 knockout mice helminth-infection may exert its impact on the TRAM-TRIF signaling pathway, contributing to the exacerbated tissue damage and enhanced fatality." (PMID 25010669, 2014). "The results from the current study suggest that in helminth co-infected MyD88 knockout mice, the ability to resist enteric bacterial infection is severely compromised because of the combined negative effects of helminth infection and MyD88 deficiency." (PMID 25010669, 2014). "However, we observed increased bacterial numbers in colonic LP in MyD88 knockout mice that are co-infected with helminth parasite, suggesting a role for MyD88 signaling and/or helminth infection in regulating intestinal mucosal barrier function." (PMID 25010669, 2014).
helminth infection (continued). "Therefore, the helminth infection is impairing this MyD88-independent recruitment of CD11b+ cells." (PMID 25010669, 2014). "To investigate whether PRR signaling modulates the outcome of a helminth infection, we first compared mice lacking the adapter protein MyD88, through which many TLRs signal, with wild-type C57BL/6 mice for their susceptibility to H. polygyrus." (PMID 25114104, 2014). "Since the MyD88-mediated pathway plays a key role in IL-1R signaling, unimpaired IL-1β–induced TNF-α and IL-6 production by macrophages from helminth-infected host suggests that the effect of the helminth infection is not on MyD88-dependent signals, but is likely to be on the TRAM/TRIF pathway." (PMID 25010669, 2014).
Hypercholesterolemia (3 papers, 2010 to 2024). An increased concentration of cholesterol in the blood. "Together, these findings indicate that the diabetic phenotype observed in Myd88-deficient mice was due at least in part to increased apoptosis in the liver possibly mediated via hypercholesterolemia." (PMID 20824098, 2010). "It has been found that MyD88 knockout and targeted knockout of TLR4-encoding genes in hypercholesterolemia mouse models can both inhibit the formation of aneurysms." (PMID 38284891, 2024). "It has been found that MyD88 knockout in hypercholesterolemia mouse models can inhibit the aneurysm formation." (PMID 38284891, 2024). "We demonstrate here that MyD88 is necessary for endothelial cell dysfunction in the face of hypercholesterolemia in vivo." (PMID 34445361, 2021). "MyD88 KO mice showed preserved endothelial function and reduced plasma cytokine expression, despite significant hypercholesterolemia." (PMID 34445361, 2021).
hypersensitivity pneumonitis (3 papers, 2008 to 2025). Hypersensitivity pneumonitis (HP) is a pulmonary disease with symptoms of dyspnea and cough resulting from the inhalation of an antigen to which the subject has been previously sensitized. "This alveolitis response to repetitive ODE exposure was reduced in MyD88 KO mice, but the perivascular lymphoid cell response (ectopic lymphoid aggregates) was not affected." (PMID 32321514, 2020).
infarction (3 papers, 2009 to 2025). A localised pathological necrosis of tissue resulting from obstruction of the blood supply usually by a thrombus, an embolus, or vascular torsion. "M2‐Exosome promoted miR‐148a expression thus ameliorated myocardial pyroptosis, cardiac injuries, myocardial Ca2+ overload and infarction through TXNIP/TLR4/MyD88/NF‐κB/NLRP3 signalling pathway in I/R rats." (PMID 39929748, 2025). "Both TLR4 and MyD88 may contribute to myocardial inflammation and infarction after I/R via NF-κB activity." (PMID 39065537, 2024). "Pretreatment with Nicorandil improved cardiac functions, infarction, and inflammation by inhibiting TLR4/MyD88/NF‐κB/NLRP3 signalling pathway thus reduced myocardial pyroptosis in rats with AMI." (PMID 39929748, 2025).
infectious colitis (3 papers, 2014 to 2021). A viral or bacterial infectious process affecting the large intestine. "In fact, mice deficient in the shared TLR signaling adaptor protein Myeloid Differentiation Primary Response 88 (MyD88) show severe intestinal inflammation and increased susceptibility to experimental or infectious colitis, due to impaired epithelial restitution and intestinal tissue repair." (PMID 24886810, 2014). "Deletion of Myd88 decreases AMP secretion, such as RegIIIγ and RELMβ and impairs epithelial cell turnover and repair leading to intestinal barrier dysfunction in experimental infectious colitis." (PMID 33414781, 2020).
intervertebral disc degeneration (3 papers, 2022 to 2024). "Necroptosis of Nucleus Pulposus Cells involved in intervertebral disc degeneration through MyD88 signaling." (PMID 36213280, 2022). "Furthermore, magnoflorine has been reported to attenuate M1 polarization-induced intervertebral disc degeneration by reducing HMGB1 expression and deactivating the MyD88/NF-kB pathway." (PMID 38493291, 2024).
intracranial hemorrhage (3 papers, 2019 to 2023). Bleeding within the SKULL, including hemorrhages in the brain and the three membranes of MENINGES. "Recently advanced studies have shown that the inhibition of MyD88-dependent TLR4 signaling is favorable in treating secondary injuries associated with brain hemorrhage." (PMID 33919485, 2021). "Hence, the information compiled here proposes that the inhibition of the MyD88 signaling cascade could be a promising therapeutic option for managing injuries secondary to brain hemorrhage." (PMID 33919485, 2021). "For example, in intracranial hemorrhage, free heme induces microglial activation via TLR4 and the MyD88/TRIF signaling pathway, resulting in the increased expression of TNF." (PMID 31358003, 2019).
kidney (3 papers, 2013 to 2024). "Thus, we challenged Toll-like receptor 4 (Tlr4) and myeloid differentiation factor 88 (Myd88) knock-out (KO) mice with N-butyl-N-(4-hydroxylbutyl)-nitrosamine (BBN), a well-known urinary bladder carcinogen." (PMID 39000291, 2024).
Klebsiella Infections (3 papers, 2012 to 2019). Infections with bacteria of the genus KLEBSIELLA. "Previous studies revealed that TRIF- and MyD88-dependent TLR signaling, which stimulate proinflammatory cytokines TNF-alpha and IL-6, contribute to host defense against Klebsiella infection." (PMID 22427976, 2012). "Interestingly, the characteristic bronchopneumonia of Klebsiella infections is virtually absent in infected MyD88−/− mice and significantly reduced in TRIF−/− mice despite high bacterial loads in both mice." (PMID 30452654, 2019).